CDH1 (cadherin 1)
Diseases named in the same sentence as CDH1 in open-access papers (continued):
Sharing a sentence is not in itself a finding about the gene and the disease.
cancer (continued). "Summary of top four selected genes (COL5A2, ITGAV, SPARC and ACTA2) which were correlated with EMT signature in 32 pan cancer cohorts was presented in radar graphs, and the well-known CDH1 (Epithelial) and VIM (Mesenchymal) genes were included as controls." (PMID 35046456, 2022). "CDH1 is involved in mechanisms regulating cell–cell adhesions, mobility, and proliferation of epithelial cells, and has a potent cancer invasion suppressing role." (PMID 36556227, 2022). "In terms of EMT marker expression, CDH1 was expressed at higher levels in the N-thy ori-3-1 cell line whereas CDH2 was more highly expressed in the cancer cell lines." (PMID 35118633, 2022). "Somatic CDH1 mutations and FGFR2 copy number gains both can facilitate cancer progress and result in more aggressive oncology conditions." (PMID 35498538, 2022). "In fact, mesenchymal-type cancer cells have low expression of epithelial markers like CDH1 and high expression of mesenchymal markers such as CDH2 gene encoding N-cadherin, fibronectin, and vimentin, among others." (PMID 36497132, 2022). "Genetic variants of unclear significance were however detected in genes such as CDH1, DICER1, MEN1, RET, CREBBP, RAD51C, or SOS1, which are linked to autosomal dominant predisposition to cancer." (PMID 35250968, 2022). "Expression of mesenchymal-like markers (ZEB1, CDH1) is correlated with AgNP sensitivity in breast, lung, and ovarian cancer cells." (PMID 35887576, 2022). "We evaluated CDH1 germline P/LP variants in 212,944 patients at one CLIA-certified laboratory (Invitae) and described their frequency in 7 cancer types." (PMID 34949788, 2022). "It promotes human SS cancer by inducing EMT by targeting CDH1 and activating the MAPK/ERK and Wnt/β-catenin signaling pathways." (PMID 36003502, 2022). "The first report for the potential role of NANOS proteins in various types of cancer was published regarding the correlation between the expression of NANOS1 and tumor suppressor gene CDH1-encoding Epithelial cadherin (E-cadherin)." (PMID 36012673, 2022). "CDH1 encodes E-cadherin, a key biomarker of epithelial–mesenchymal transition (EMT) in cancer cells and a mediator of cell–cell adhesion in epithelial tissues." (PMID 35054979, 2022). "For example, in cancer cell line models of NSCLC, transcription factor Six2′s overexpression caused promoter methylation of CDH1, inhibiting E-cadherin expression and enhancing stemness and chemosensitivity." (PMID 35563709, 2022). "EMT is important in cancer progression, and E-Cadherin (CDH1) appears to be downregulated during EMT." (PMID 35563098, 2022). "Down-regulation of CDH1 by the EMT TFs has been shown to increase cancer cell proliferation, invasiveness, and/or metastasis." (PMID 34708244, 2022). "One of the most important mechanisms in cancer metastasis is EMT occurring due to decrease in CDH1/E-cadherin levels and increase in CDH2/N-cadherin and VIM levels." (PMID 35317831, 2022). "In summary, CDH1 is the best cancer-specific marker in this MS-based assay that can effectively discriminate the cancerous-PEs from each of the other PE groups." (PMID 35197508, 2022). "As BC is a highly heterogeneous malignant neoplasm, we investigated CDH1 expression in different subtypes of BC in GEPIA." (PMID 35784532, 2022). "In contrast, 5-azacytidine induces CDH1 demethylation, leading to the retention of epithelial characteristics of cancer cells and reduced sensitivity to ferroptosis." (PMID 33574983, 2021). "Cancer cells have multiple mechanisms of CDH1 downregulation, which appears to be a prerequisite for EMT as CDH1 has multiple binding sites for EMT-TFs." (PMID 33566221, 2021).
cancer (continued). "The results of PPI demonstrated that the five TFs were tightly associated with many critical cancer related factors or pathways, such as SMAD4, MMP13, IL-5, IL-2, CYP2E1, CCNE1 and CDH1." (PMID 34405021, 2021). "Firstly, CDH1 was found to be significantly hypermethylated in cancer tissues compared to control healthy tissue as well as compared to oral lesions." (PMID 34835040, 2021). "TCGA data analysis showed that high NMUR2 levels are characteristic of cancers with low differentiation and increased invasiveness, as represented by decreased CDH1 expression and increased MMP1 expression." (PMID 34493299, 2021). "Increased expression of either SIX1 or SIX2 in several cancer types reduced the level of CDH1 through either activating known repressors of CDH1, such as Zeb proteins, or by CDH1 promoter methylation." (PMID 34490256, 2021). "We also found strong correlations between MES and ADRN TFs with markers of cancer cell stemness and cancer cell motility including CDH1, CDH2, NANOG, SOX2, TWIST1, VIMENTIN, and Fibronectin across cancers." (PMID 35201514, 2021). "Growing evidence has demonstrated that loss of CDH1 expression triggers epithelial-mesenchymal transition (EMT), which endows cancer cells with stem-like traits." (PMID 34294686, 2021). "The mean age at diagnosis for individual CDH1 mutant carriers with GC was 40.6 years (range 21–79), and for other cancers 50.6 years (range 23–63)." (PMID 34066044, 2021). "The expression levels of CDH1 were negatively correlated with OSCAR in 12/20 types of cancer, especially BLCA (r=-0.296), COAD (r=-0.275), PRAD (r=-0.377), and READ (r=-0.295)." (PMID 34093786, 2021). "In a recent large cohort of 95 patients with CDH1 mutations and a family history of HDGC having undergone PTG, cancer foci were found in 89% of specimens, consistent with our detection rate of 85%." (PMID 34073553, 2021). "For women with a PALB2, CDH1 or NF1 mutations, the NCCN recommends an annual mammogram and annual MRI beginning at age 30, unless the age of cancer diagnosis within the family was earlier." (PMID 34573353, 2021). "On the other hand, there is evidence of TWIST recruiting the NuRD complex to mediate CDH1 gene promoter transcription repression to promote EMT in cancer cells." (PMID 33669496, 2021). "SNAI1-induced EMT in cancer cells promotes a more fibroblast-like appearance and increases the invasive behavior by suppressing CDH1 and β-catenin expression through elevated vimentin expression." (PMID 34455105, 2021). "The core component genes of the pathway CTNNB1, encoding for β catenin, APC and CDH1, encoding for E cadherin, are less frequently mutated, but also their prevalence is higher in PIK3CA mutated cancers than wild-type ones." (PMID 33435133, 2021). "In contrast, the increased E-cadherin protein expression (Cdh1 gene) induced by fructose supplementation will potentiate cell-to-cell contact inhibition, reducing the mobility and growth of cancer cells." (PMID 34650394, 2021). "In CD45-DB samples, downregulation of SNAI1 and upregulation of miR-9 were found in patients with HER2+ tumors, and upregulation of CDH1 in grade 3 cancers, respectively." (PMID 35008529, 2021). "After dividing dogs into groups according to breed we found upregulation of RAC1 together with GRB2 and CDH1 in carcinoma-solid compared to carcinoma-simple in mixed-breed dogs." (PMID 34679042, 2021). "We also validated the CDH1 gene promoter in the same groups of cancer samples and healthy controls by Methylation-Specific PCR (MSP), and the findings are in concordance with the Infinium MethylationEPIC BeadChip array findings (data not presented)." (PMID 32961999, 2020). "It was also reported that CDH1 was found overexpressed in many malignant tumor samples, along with other APC substrates." (PMID 32805721, 2020).
cancer (continued). "Down-regulation of Cdh1 is observed in several cancers and many Cdh1 substrates, such as M/S-phase cyclins and DNA replication factors are frequently overexpressed in tumors." (PMID 32560247, 2020). "Functional experiments showed that miR-514b-5p triggers EMT and invasion of cancer cells via targeting cadherin 1 (CDH1, also named E-cadherin 1) and claudin 1 (CLDN1)." (PMID 33066509, 2020). "CDH1 carriers face several challenges, including the burden of cancer treatment, if already affected by DGC or LBC, and the need to decide upon prophylactic surgery if still unaffected." (PMID 32560361, 2020). "The same gene (CDH1) is also among the top fifteen genes that are significantly hypermethylated on different sites across the genome in cancer tissues compared to lesions." (PMID 32961999, 2020). "The hub gene TYMS is also involved in one carbon pool by folate pathway; FOS, JUN, and CDH1 genes are involved in pathways in cancer; and JUN and FOS genes are involved in the oestrogen signalling pathway." (PMID 32093341, 2020). "The transcription factor Snail1, together with LOXL2, would participate in downregulating the CDH1 gene and other heterochromatin transcripts, giving rise to transformation of cancer epithelial cells into mesenchymal cells (through EMT)." (PMID 31462706, 2020). "In contrast to the gradual increase of VE-cadherin expression in cancer cells, the protein amounts of E-cadherin in MCF7 and cadherin-11 in MDA-MB-231 cells decreased significantly after 24 h of co-culturing." (PMID 32752204, 2020). "The AR functions in cell migration and cancer metastasis by regulating its major target genes E-cadherin (CDH1) and vimentin (VIM)." (PMID 32847068, 2020). "Transcriptional expressions of VIM were significantly elevated in cancer tissue compared with normal tissues, while expression of CDH1, a key epithelial marker, was significantly decreased in cancer tissue in multiple datasets." (PMID 31915310, 2020). "Two (EPCAM and CDH1) reflect the presence of malignant epithelium in cancer‐replaced nodes and its absence in cancer‐free nodes." (PMID 31755096, 2020). "Given the complexity and the rarity of this syndrome, CDH1 carriers should always be treated in a multidisciplinary fashion and in high-specialized cancer centers." (PMID 32560361, 2020). "Cadherin-1 (CDH1), in the classical cadherin superfamily, is associated with cancer proliferation and invasiveness." (PMID 32321971, 2020). "We used the CBioPortal database to analyze the mutual relation linking AGR2 and E-cadherin (CDH1) in cancer cell lines listed in the Cancer Cell Line Encyclopedia (CCLE)." (PMID 32570918, 2020). "In this study, we found the CDH1 gene to be significantly hypermethylated on specific sites in the genome (body) on a high second place in cancer tissues in comparison to control tissues." (PMID 32961999, 2020). "We report the significance of CDKN2A hydroxymethylation by HPV status, as well as many other cancer-related genes, such as CDH1, TIMP3 and SFRP4." (PMID 33203436, 2020). "We also found that overexpression of PDCD10 increased cancer metastasis by down-regulating CDH1, enhancing VIM expression, and inducing EMT." (PMID 32483426, 2020). "We next compared the expression patterns of VIM (vimentin) and CDH1 (E-cadherin) with those of Sipa1 using qRT-PCR in the cancer cell lines studied herein." (PMID 32193333, 2020). "Previous studies have shown that in actively dividing cancer cell lines, simultaneous depletion of CDH1 and CDC20 adaptor proteins, together with EMI1, i.e., three subunits of the APC/C, leads to a completely dysfunctional APC/C and a prolonged S-phase." (PMID 32295923, 2020).
cancer (continued). "According to the data published in the current literature, the number of pT1a carcinoma foci found in total gastrectomy specimens from CDH1 carriers, ranged from 1 to 487 and the size varied from <0.1 mm to 16 mm." (PMID 32560361, 2020). "These ZEB1/2-CtBP1/2 repressor complexes are important for downregulating the epithelial marker E-cadherin (CDH1) during carcinoma progression and during developmental processes such as neurulation and pituitary lactotrope differentiation." (PMID 32796736, 2020). "Together, these results demonstrate that autophagy inhibition is able to activate the EMT program, specifically in RAS-mutated cancer cells, which is supported by the induction of EMT transcription factors and, consequently, a reduction in CDH1 expression." (PMID 30782064, 2019). "We are taking a synthetic lethal approach to identify druggable vulnerabilities in CDH1-mutant cancers." (PMID 30066183, 2019). "The result showed that CDH1 expression between cancer cells was much lower than between normal epithelial cells." (PMID 31443371, 2019). "The difference in the impact of Esrp2 and Esrp1 overexpression on Cdh1 levels at day 5 is consistent with a previous study demonstrating that the knockdown of Esrp paralogs has different effects on Cdh1 expression in the context of cancer cell motility." (PMID 30704403, 2019). "Bioinformatics analysis revealed that SNPs in six genes (NCOR1, GATA3, CDH1, ATM, AKT1, and PTEN) were significantly associated with the corresponding expression levels and were involved in multiple pathways involved in cancer development." (PMID 30883028, 2019). "Promoter hypermethylation was identified as one of the main mechanisms that inactivates CDH1 during the progression of various cancers, including GC." (PMID 31212809, 2019). "Mutations in six genes (NCOR1, GATA3, CDH1, ATM, AKT1, and PTEN) were significantly correlated with the corresponding expression levels, and were enriched and involved in multiple cancer‐related pathways." (PMID 30883028, 2019). "The top enriched disease and function pathways for the CDH1-specific and CDH2/CDH1-shared protein sets were cellular organization and cancer-related categories." (PMID 30630894, 2019). "The calcium-dependent E-cadherin (CDH1) is known to suppress tumorigenicity, and several mechanisms to impair CDH1 function were reported in cancer including epithelial to mesenchymal transition (EMT)." (PMID 31426484, 2019). "SNAI2 acts as an inhibitory transcription factor that binds to E-box motifs of CDH1 and represses its transcription in cancer." (PMID 31749661, 2019). "It specifically inhibits the transcription of anticancer genes such as CDH1/E-cadherin and activates mesenchymal markers to promote the metastasis of most cancers." (PMID 30736337, 2019). "It inhibits the activity of the E-cadherin/CDH1 gene and subsequently promotes metastasis of most cancers." (PMID 30736337, 2019). "CDH1 is a direct target of both miR-25 and miR-92a, in which levels were highly increased in carcinoma cells, where the expression of E-cadherin was repressed, leading to the increased invasiveness of cells." (PMID 31752264, 2019).
cancer (continued). "ZEB, SNAIL, TCF3 and TWIST were originally described due to their ability to repress the invasion suppressor gene CDH1, encoding the cell adhesion protein E-cadherin, whose functional loss is considered a hallmark of EMT during carcinoma progression." (PMID 31071975, 2019). "GS cancers often showed mutations in genes responsible for cell adhesion, such as RHOA, CDH1 and CLDN18/ARHGAP." (PMID 29721214, 2018). "Support for this idea comes from studies using SIRT2, an antitumor and lifespan-extending protein, which activates the APC by deacetylating CDC20 and CDH1; SIRT2-deficient mice exhibited higher levels of cancer and elevated levels of APC substrates." (PMID 29954095, 2018). "Pathway enrichment analysis was most significant for evidence of epithelial-mesenchymal transition (EMT) in the C1 tumors, with concordant loss of E-cadherin (CDH1) and upregulation of CXCL14, both prognostic biomarkers in diverse other cancers 23–25." (PMID 30202034, 2018). "The expression of ANXA2 and CDH1 was evaluated in cancer (at different stages) and healthy datasets." (PMID 30050103, 2018). "High CDH1 and low IL-1B in cancer cells induce MSC organization into a niche like formation, dependent on direct cell–cell contact, in vitro." (PMID 29760166, 2018). "The inverse correlation between E-cadherin expression and hypermethylation of the CDH1 gene promoter has been confirmed in many cancers." (PMID 30544763, 2018). "LSD1 adjusts EMT through demethylation of CDH-1 gene involved in invasion and metastasis of cancer cells." (PMID 28121627, 2017). "Given the pivotal role of ZEB1 in downregulating CDH1 and inducing the loss of cell polarity, ZEB1 drives the EMT and cancer progression." (PMID 28088787, 2017). "For the first time, we evaluated by digital PCR the expression of CDH1 and CDH1a transcripts in cancer and normal tissue samples from 32 patients with intestinal-type gastric cancer." (PMID 27861150, 2017). "We further focused on four key genes (CABYR, FOXF2, TLE4, and CDH1 ) related to proliferation, apoptosis, tumorigenesis, invasion and metastasis of cancer cells." (PMID 28121627, 2017). "On the other hand, the damaging CDH1 T340A, damaging NRAS G138R and tolerated MLH-1 R148Q variant were exclusively present in the cancer group." (PMID 29069792, 2017). "Then, the expression levels of genes zeb1 and cdh1 and the probabilities of an individual cancer cell appearing in three phenotypic states are compared with those of the human breast SUM159 line." (PMID 28852133, 2017). "Such cancer type–specific associations were also seen for PIK3CA, KRAS, GATA3, CTCF, CDH1, and ARIDA1." (PMID 29125844, 2017). "Our analysis show that younger patient cancers with Gleason score equal 8 and 9 are characterized by significant overexpression both of CDH1 and CTNNB1." (PMID 29206234, 2017). "We examined CDH1 and CTNNB1 mutations in a wide variety of anatomic sites that collectively account for most cancer cases." (PMID 29156750, 2017). "The novel miRNA (isomiR-4534) identified in this study is generated by non-canonical editing of the pri/pre-miR-4534, is abundant in cancer cells compared to normal epithelial cells and suppresses CDH1 expression when transfected in S-paRNA expressing cells." (PMID 28555645, 2017). "Specifically, we examined somatic mutations in CDH1 and CTNNB1 in thousands of clinical primary carcinomas from 13 anatomic sites." (PMID 29156750, 2017).